RNU6-824P (RNA, U6 small nuclear 824, pseudogene)
Gene: Small nuclear RNA gene on chromosome 6 (154,825,176 to 154,825,279, reverse strand). Ensembl gene ENSG00000200594.
Homologues: Orthologues: chimpanzee U6 (99% identical), macaque U6 (91% identical), guinea pig U6 (71% identical). Paralogues in human: RNU6-268P (88% identical), RNU6-16P (88% identical), RNU6-11P (87% identical), RNU6-37P (87% identical), RNU6-39P (87% identical), RNU6-45P (87% identical), RNU6-80P (87% identical), RNU6-843P (87% identical), RNU6-86P (87% identical), RNU6-1181P (86% identical), RNU6-12P (86% identical), RNU6-13P (86% identical), and 1288 more.